TRAF6 (TNF receptor associated factor 6)
Diseases named in the same sentence as TRAF6 in open-access papers (continued):
Sharing a sentence is not in itself a finding about the gene and the disease.
prostate carcinoma (23 papers, 2016 to 2025). A carcinoma that arises from epithelial cells of the prostate gland. "In prostate cancer, TRAF-6-mediated Lys6-linked ubiquitination of the TGF-βRI intracellular domain is important for the modulation of TGF-β and regulation of other genes controlling the cell cycle, proliferation, differentiation, and migration." (PMID 38543112, 2024). "Taken together, these observations suggest that the endosomal proteins APPL1 and APPL2 are important for the nuclear trafficking of TβRI-ICD, which is regulated by TRAF6 and is linked to prostate cancer progression." (PMID 26583432, 2016). "Moreover, APPL proteins were found to be expressed at high levels in aggressive prostate cancer tissues, and to be associated with TβRI in a TRAF6-dependent manner." (PMID 26583432, 2016). "In the study, SKP2 modulated H3K4me3 levels by regulating TRAF6-mediated K63-linked ubiquitination of JARID1B, a key demethylase of H3K4me3, thereby influencing prostate cancer migration and recurrence." (PMID 40771930, 2025). "Resveratrol has been shown to mediate the degradation of TRAF6 and decrease the proliferation and migration of prostate cancer cells." (PMID 36769122, 2023). "In corroboration with these findings, the suppression of TRAF6 by shRNA impairs Akt activation in prostate cancer cells, suppresses tumor formation in the xenograft tumor model and potentiates apoptosis induced by chemotherapy agents." (PMID 36769122, 2023). "Previous studies have linked TRAF6 to TGFβ-induced activation of p38/MAPK signaling, for example, in prostatic cancer cell migration." (PMID 31243287, 2019). "Recent study showed that TRAF6 promotes TGFβ‐induced invasion in prostate cancer 51, which is consistent with our results." (PMID 29193723, 2018). "Recently, TRAF6 has been found to play a role in ubiquitination processes in prostate cancer." (PMID 40771930, 2025). "DNMT1 promotes prostate cancer progression and metastasis by enhancing TRAF6 transcription and facilitating TNF receptor-associated factor 6 (TRAF6)-mediated ubiquitination of EZH2, underscoring its pivotal role in tumorigenesis and potential as a therapeutic target." (PMID 40034825, 2025). "Additionally, the formation of a complex between TGF-β receptor and the ubiquitin ligase TRAF6 was discovered to play a role in the advancement of mitosis and cytokinesis in prostate cancer cells." (PMID 38801557, 2024). "In addition, evidences exhibited that TRAF6 is required for transforming growth factor-β (TGF-β) induced prostate cancer cell migration through PI3K-AKT signaling pathway." (PMID 32905356, 2020). "We identified previously that c-Jun, a member of AP-1 transcription factors, is activated by TGF-β in a TRAF6-dependent manner leading to invasion of prostate cancer cells and that the Smad7-APC complex links TβRI to the microtubule system to promote migratory responses of prostate cancer cells." (PMID 32888405, 2020). "Particularly, TRAF6, initially recognized as a cytoplasmic adapter protein, has recently been established as a key regulator of EZH2 stability in breast and prostate cancers." (PMID 39043634, 2024). "The study showed that EMT procedure was significantly blocked after inhibition of TRAF6 expression in HNSCC cell lines, while over-expression of TRAF6 up-regulated SLUG expression benefiting EMT in prostate cancer cells." (PMID 32905356, 2020). "As a key transfer adaptor protein that transduces the Wnt3a/β-Catenin pathway, TRAF6 upregulated the mRNA expression of β-Catenin and subsequently activated Wnt target genes such as c-Myc and LRP5 in human prostate cancer PC3U cells." (PMID 32905356, 2020). "Additionally, miR-146a promotes NF-kB signaling in oral, cervical, breast, and prostate cancers through the targeting of IRAK1 and TRAF6, and it enhances cell growth and proliferative signaling in several cancers—including breast, liver, lung, prostate, and gastric—by targeting EGFR." (PMID 40277937, 2025).
rheumatoid arthritis (22 papers, 2008 to 2026). A chronic, systemic autoimmune disorder characterized by inflammation in the synovial membranes and articular surfaces. "The single nucleotide polymorphisms (SNPs) of TRAF6 on Chromosome 11 are linked to autoimmune disorders, including rheumatoid arthritis (RA), systemic lupus erythematosus (SLE), and idiopathic inflammatory myopathy." (PMID 40136419, 2025). "It prevents an overstimulation of the inflammatory response through its recognised target genes, IRAK-1 and TRAF-6, and its dysregulation is associated with many inflammatory diseases including rheumatoid arthritis (RA) and systemic lupus erythematosus (SLE)." (PMID 28103790, 2017). "Genes of interest are trafficking protein, kinesin binding 2 (Trak2) on chromosome 1 and TNF receptor–associated factor 6 (Traf6) on chromosome 2 because they were discovered together in several previously reported GWAS studies associated with atopic dermatitis, psoriasis, and rheumatoid arthritis." (PMID 29566008, 2018). "For example, A20 has been identified as a negative regulator of the core cross-talk element TRAF6, and several studies have shown that deficiencies in A20 are associated with some autoimmune diseases, including rheumatoid arthritis, systemic lupus erythematosus, and Crohn's disease." (PMID 20497537, 2010). "Interestingly, the AgNP-associated loci identified Trak2 and Traf6 on chromosomes 1 and 2, previously reported together as genetic variants associated with several common inflammatory diseases including atopic dermatitis, psoriasis, and rheumatoid arthritis." (PMID 29566008, 2018). "For example, miR-146b suppressed TRAF6 to inhibit the damage to the glomerular system in lupus erythematosus and rheumatoid arthritis." (PMID 37909731, 2023). "In preclinical in vivo mouse models, C25-140, an inhibitor of the TRAF6-Ubc13 interaction, can reduce NF-κB activation, improving the disease outcomes for autoimmune psoriasis and rheumatoid arthritis." (PMID 33294443, 2020). "Importantly, a TRAF6 small molecular inhibitor was recently described with activity in primary human and mouse cells, resulting in improved disease outcomes in rheumatoid arthritis and psoriasis mouse models." (PMID 36172375, 2022). "Elevated levels of miR-146a was found in synovial fibroblast and blood mononuclear cells of rheumatoid arthritis patients while the levels of IRAK1 and TRAF6 mRNAs were similar to those of controls." (PMID 28319200, 2017). "Recently, TRAF6 expression was found to be upregulated in systemic lupus erythematosus (SLE), rheumatoid arthritis (RA), hyperplastic thymuses and MG patient serum." (PMID 35978310, 2022). "We predicted miRNAs with regulatory impact on NFKB1 and TRAF6 gene expression and selected the miR-194-5p, miR-124-3p, miR-9-5p, and miR-340-5p and their target genes for expression analyses on CD14+ monocytes from rheumatoid arthritis (RA) patients and healthy controls." (PMID 39058384, 2024). "USP5 can also stabilize TRAF6 by deubiquitination, but contrary to the results of USP3, overexpression of USP5 increases the activation of NF-κB pathway, promotes the release of NF-κB, and then up-regulates the secretion of pro-inflammatory cytokines such as IL-1β in rheumatoid arthritis (RA)." (PMID 40226783, 2024). "However, the role of TRAF6 may be pro-inflammatory in some circumstances since a small molecule inhibitor, C25-140, that disrupts binding of TRAF6 to its partner E2 ligase Ubc13, results in decreased TCR-induced activation of NF-κB and decreased psoriasis and rheumatoid arthritis in murine models." (PMID 31756921, 2019).
autoimmune disease (21 papers, 2010 to 2025). A disorder resulting from loss of function or tissue destruction of an organ or multiple organs, arising from humoral or cellular immune responses of the individual to their own tissue constituents. "IL-17 is linked to localized inflammation and pathogenic in certain autoimmune diseases, in which IL-17 binds to its canonical receptor IL-17RA and activates TRAF6 and the subsequent signaling cascade." (PMID 37270623, 2023). "This conclusion has important implications for autoimmune diseases where polymorphisms in genes such as Traf6, Relb, and Rel reduce expression and transcriptional activity of RelB in thymus, including loss of function." (PMID 29872433, 2018). "Therefore, TRAF6 is associated with diverse abnormalities including different cancer types, autoimmune diseases, neurodegenerative disorders, and inflammatory diseases." (PMID 38004473, 2023). "Therefore, TRAF-6-deficient T cells can affect immune homeostasis, and autoimmune disease can appear." (PMID 28219358, 2017). "Although TRAF6 plays an indispensable role in regulating the development, homeostasis, and activation of immune cells, the excessive activation of immune cells may be a cause for the development of autoimmune diseases." (PMID 33294443, 2020). "This regulatory mechanism helps to maintain immune system stability in miiuy croaker by downregulating TRAF6 expression, thereby preventing the onset of autoimmune diseases." (PMID 37958869, 2023). "Recent studies also documented that high levels of TRAF6 were observed in serum patients with autoimmune diseases including systemic lupus erythematosus, rheumatoid arthritis, and myasthenia gravis." (PMID 38004473, 2023). "Together, our findings demonstrate a novel role for miR-146a and TRAF6 in the extrafollicular B-cell responses, which have recently been tied to autoimmune disease pathogenesis." (PMID 36172375, 2022). "This has implications in cell specific miR (i.e. miR-146a-mimic conjugated to CpG) and molecular gene target applications (TRAF6 inhibitors, etc) for future therapeutic application in autoimmune diseases, that are currently being explored." (PMID 36172375, 2022). "Our work highlights the pathogenetic role of miR-146a and the potential of pharmacologic inhibition of TRAF6 in autoimmune diseases in which miR-146a is deregulated." (PMID 36172375, 2022). "Blocking the interaction of TRAF6 with its upstream or downstream molecules is also an effective treatment strategy for autoimmune diseases." (PMID 33294443, 2020). "In fact, in addition to autoimmune diseases and cancer, TRAF6 is also involved in the pathogenesis of other diseases, including cardiovascular diseases and central nervous system diseases." (PMID 33294443, 2020). "Although the pathogenesis and etiology of autoimmune diseases and cancer are not fully understood, it is worth noting that existing studies have shown that TRAF6 is involved in the pathogenesis and development of a variety of these diseases." (PMID 33294443, 2020). "Given the critical role of TRAF6 in DC activation and survival, Treg cell production, and Th17 differentiation, TRAF6 is a suitable therapeutic target for autoimmune diseases." (PMID 33294443, 2020). "In this review, we mainly discuss the role of TRAF6 in immune cells and its relationship to the development of certain autoimmune diseases and cancer." (PMID 33294443, 2020). "Herein, we reviewed the role of TRAF6 in certain immune cells, as well as the function and potential effect of TRAF6 in autoimmune diseases and cancer." (PMID 33294443, 2020). "Previous studies have shown that the TRAF6 expression is closely related to many diseases, such as cancer and autoimmune diseases." (PMID 30622431, 2018).
autoimmune disease (continued). "Expression of SNHG16, TLR4 and TRAF6 and cell death processes were examined in lung tissues and peripheral blood (PB) leukocytes from AH patients associated with SLE and other autoimmune diseases, and in the lungs and spleen from a pristane-induced C57BL/6 mouse AH model." (PMID 37700342, 2023). "Notably, TRAF6 facilitates the activation of NF-κB in numerous biological and pathological occurrences, encompassing inflammation, autophagy, and autoimmune diseases." (PMID 37957714, 2023). "However, a role for TRAF6 expression as a proinflammatory marker has been demonstrated in several autoimmune diseases, such as SLE and RA." (PMID 35978310, 2022). "Given that reduced TRAF6 expression levels are correlated with improvement in various autoimmune disease models and our results showed a strong relationship between TRAF6 in B cells and disease severity, TRAF6 might be a potential therapeutic target in MG." (PMID 35978310, 2022). "Current researches indicate that TRAF6 could be involved in the pathogenesis of a variety of autoimmune diseases, including RA, SLE, LN, and MS." (PMID 33294443, 2020). "Here, we summarize the important role of TRAF6 in immunity and autoimmune diseases." (PMID 33294443, 2020). "The pathogenesis of various autoimmune diseases is related to the regulation of TRAF6 by miR-146a." (PMID 33294443, 2020). "In fact, there have been many attempts to treat autoimmune diseases with TRAF6 as a target." (PMID 33294443, 2020). "This evidence suggests that reducing the expression of TRAF6 may be a useful strategy for the treatment of autoimmune diseases." (PMID 33294443, 2020). "Our review indicates that TRAF6 may be a novel target for autoimmune diseases and cancer." (PMID 33294443, 2020). "However, the expression of TRAF-6 in some other autoimmune diseases exhibits the opposite trend." (PMID 28219358, 2017).
osteoarthritis (21 papers, 2012 to 2025). A noninflammatory degenerative joint disease occurring chiefly in older persons, characterized by degeneration of the articular cartilage, hypertrophy of bone at the margins and changes in the synovial membrane. "In contrast, miR-146a modulates the TLR4/IL-1 receptor-associated kinase 1/TNF receptor-associated factor 6 signaling axis and nuclear NF-κB-mediated inflammation, thereby linking it directly to cartilage degradation and osteoarthritis progression." (PMID 41403440, 2025). "Other groups also revealed that YAP/TAZ attenuated NF-κB signaling by directly inhibiting IKKα/β activation in an osteoarthritis murine model and by associating with TRAF6 and facilitating TRAF6 degradation in vascular inflammation." (PMID 32849504, 2020). "Furthermore, these exosomes downregulate TNF receptor-associated factor 6 (TRAF6) expression and inhibit nuclear factor-kappa B (NF-κB) signaling pathways, ultimately mitigating osteoarthritis-related structural deterioration of articular cartilage and chondrocyte apoptosis." (PMID 41382397, 2025). "miR-125b-5p was found to regulate the expression of inflammatory genes in human osteoarthritis chondrocytes, in a manner that involved the targeting of the TRAF6/MAPKs/NF-κB signaling pathway." (PMID 39126012, 2024). "Levels of both BCL-2 and TRAF-6 proteins are elevated in inflammatory disorder conditions such as osteoarthritis and rheumatoid arthritis." (PMID 34550907, 2021). "Such as has_circ_0136474, which regulates IL-1β-Induced chondrocyte injury through miR-766-3p/DNMT3A Signaling Pathway; Circ-BRWD1, which contributes to osteoarthritis development through the modulation of miR-1277/TRAF6 axis." (PMID 34652255, 2021). "It has been reported that TRAF-6 and BCL-2 proteins are closely associated with inflammatory disorder, such as osteoarthritis." (PMID 34550907, 2021). "For example, the TRAF-6 level in the synovial tissue of patients with RA was higher than that in the synovial tissue of patients with osteoarthritis (OA), suggesting that TRAF-6 mediates the inflammatory response involved in synovial inflammation and joint destruction in RA." (PMID 28219358, 2017). "It has been reported that TRAF6 was up-regulated in basal RA-FLS compared to osteoarthritis (OA)-FLS, and lipopolysaccharide (LPS) stimulation could induce the up-regulation of TRAF6 in RA-FLS." (PMID 22656185, 2012). "circBRWD1 demonstrated its ability in modulating the miR-1277/TRAF6 and miR-513a-5p/TNPO1 axes in osteoarthritis and hepatocellular carcinoma respectively." (PMID 41327336, 2025). "In terms of osteoarthritis, naringenin was reported to attenuate inflammation and apoptosis of osteoarthritic chondrocytes via the TLR4/TRAF6/NF-κB pathway." (PMID 40027098, 2025). "This further supports the notion that F-MSCs-Exo can deliver miR-146b-5p to the rat knee joint, silence TRAF6, and subsequently inhibit the PI3K/AKT/mTOR pathway to protect chondrocytes in osteoarthritis." (PMID 38105181, 2023). "The results revealed that naringenin alleviated the pathological symptoms of osteoarthritis in mice, reduced the expression of TLR4 and TRAF6, and the phosphorylation of NF-κB in knee cartilage tissue." (PMID 37953787, 2023). "The findings clearly suggested that MAPK and NF-κB pathways may be responsible involving the TRAF-6 and BCL-2 genes which might contribute for the ameliorative potential of RT in osteoarthritis induced chondrocytes." (PMID 34550907, 2021).
hepatocellular carcinoma (20 papers, 2007 to 2026). A malignant tumor that arises from hepatocytes. "Analogously, AJUBA, an oncogenic protein regulated by SE and linked to an unfavorable prognosis, engages TRAF6 to facilitate the activation of AKT signaling in hepatocellular carcinoma (HCC)." (PMID 38844984, 2024). "In hepatocellular carcinoma cells, TRAF6 has oncogenic potential by interacting with and ubiquitinating HDAC3 with K63-linked ubiquitin chains, which leads to the dissociation of HDAC3 from the c-Myc promoter." (PMID 38609495, 2024). "Via down-regulation of TRAF6, miR-146a-5p suppressed hepatocellular carcinoma (HCC) cell proliferation and invasion in vitro and inhibited tumor formation in vivo and in vitro." (PMID 33015045, 2020). "In human hepatoma cells, IL-17 induces C/EBPβ activation via TRAF6 and TRAF6-dependent p38 MAPK and ERK1/2 activation." (PMID 31156649, 2019). "Initially, HCV infection activates GP73 in patients’ serum, primary human hepatocytes (PHHs) and human hepatoma cells by regulating MAVS/TRAF6 and MEK/ERK pathway." (PMID 28394926, 2017). "It has been revealed that TRAF6 may contribute to the metastasis and progression of hepatocellular carcinoma and could serve as a promising target in the treatment of hepatocellular carcinoma." (PMID 38678587, 2024). "Moreover, current research shows that pharmacological suppression of TRAF6 activity with the usage of TIP to modulate its pathway restrained c-Mycexpression as well as efficiently repressed hepatocellular carcinoma growth." (PMID 39243105, 2024). "GP73 expression is activated and correlated with IFN-β production during HCV infection in patients’ serum, primary human hepatocytes (PHHs) and human hepatoma cells through mitochondrial antiviral signaling protein (MAVS), TNF receptor-associated factor 6 (TRAF6) and MEK/ERK pathway." (PMID 28394926, 2017). "Circ 0001955, TRAF6, and MAPK11 are upregulated in hepatocellular carcinoma, whereas miR 145 5p and miR 516a 5p are downregulated." (PMID 41465470, 2025). "Collectively, these mechanisms allow circ0001955 to restore the carcinogenic activity of ARF6, SPATS2, TRAF6, and MAPK11 in chronically HCV-infected hepatocytes, promoting the initiation and progression of hepatocellular carcinoma." (PMID 41465470, 2025). "In line with this, the putative targets of miR-146b-5p including TRAF6 and NOVA1 have been shown to increase chemoresistance in OSCC and hepatocellular carcinoma, respectively." (PMID 36703917, 2022). "As the presence of hepatocellular carcinoma (HCC) is associated with higher mortality and shorter follow-up, we also confirmed an association of the TRAF6 haplotype with SBP for the subgroup of patients without HCC." (PMID 28687809, 2017).